LINC01876 (long independently transcribed non-coding RNA 1876)
Synonyms: uc.83
Gene: Long non-coding RNA gene on chromosome 2 (156,010,644 to 156,320,306, reverse strand). Ensembl gene ENSG00000226383.
Diseases named in the same sentence as LINC01876 in open-access papers:
LINC01876 is named in the same sentence as 1 disease in open-access papers, as found by Europe PMC text mining. Sharing a sentence is not in itself a finding about the gene and the disease. The quoted sentences say what the papers report.
major depressive disorder (1 paper, 2023). An episode of depression lasting two or more weeks without an intervening episode of mania. "LINC01876 is a previously uncharacterized lncRNA, but we have noted that there is a T > C single-nucleotide polymorphism in the L1-derived promoter region of LINC01876 that has been linked to major depressive disorders in a genome-wide association meta-analysis." (PMID 37910626, 2023).